TM4SF5 (transmembrane 4 L six family member 5)
Description:
Acts as a lysosomal membrane arginine sensor. Forms a complex with MTOR and SLC38A9 on lysosomal membranes in an arginine-regulated manner, leading to arginine efflux which enables the activation of mTORC1 which subsequently leads to RPS6KB1 and EIF4EBP1 phosphorylations. Facilitates cell cycle G1/S phase progression and the translocation of the CDK4-CCND1 complex into the nucleus. CDKN1B and RHOA/ROCK signaling activity are involved in TM4SF5-mediated acceleration of G1/S phase progression.
Tractability: Antibody: UniProt places it where antibodies can reach, with high confidence; its Gene Ontology location is reachable by antibodies, with high confidence; UniProt predicts a signal peptide or a membrane-spanning region.
Gene: Protein-coding gene on chromosome 17 (4,771,849 to 4,783,213, forward strand). Ensembl gene ENSG00000142484.
Subcellular location: Lysosome membrane; Cell membrane
Subcellular location (Human Protein Atlas): Cell Junctions; Plasma membrane; Nucleoplasm
Gene Ontology:
Molecular function: arginine binding; protein binding
Biological process: regulation of G1/S transition of mitotic cell cycle
Cellular component: lysosomal membrane; plasma membrane; membrane
Genetic constraint (gnomAD): Loss-of-function variants: 18 observed, 23.75 expected, observed/expected ratio (o/e) 0.76, 90% interval 0.52 to 1.12. The upper end of that interval is the gene's LOEUF score, 1.12, which puts it in group 4 of 6, group 1 being the genes least tolerant of losing a copy. Missense variants: 243 observed, 274.99 expected, observed/expected ratio (o/e) 0.88, 90% interval 0.8 to 0.98. Synonymous variants: 112 observed, 116.15 expected, observed/expected ratio (o/e) 0.96, 90% interval 0.83 to 1.13.
Homologues: Orthologues: chimpanzee TM4SF5 (98% identical), macaque TM4SF5 (93% identical), dog TM4SF5 (83% identical), pig TM4SF5 (83% identical), mouse Tm4sf5 (82% identical), rat Tm4sf5 (81% identical), guinea pig TM4SF5 (80% identical), zebrafish tm4sf5 (54% identical). Paralogues in human: TM4SF1 (46% identical), TM4SF4 (41% identical), TM4SF18 (34% identical), TM4SF19 (34% identical), TM4SF20 (30% identical).
Diseases named in the same sentence as TM4SF5 in open-access papers:
TM4SF5 is named in the same sentence as 35 diseases in open-access papers, as found by Europe PMC text mining. Sharing a sentence is not in itself a finding about the gene and the disease. The quoted sentences say what the papers report.
hepatocellular carcinoma (18 papers, 2011 to 2026). A malignant tumor that arises from hepatocytes. "In hepatocellular carcinoma, where transmembrane 4 L six family member 5 (TM4SF5), a tetraspanin-type protein, is implicated in their migration and invasion, a high incidence of Y845 phosphorylation of EGFR was demonstrated." (PMID 23702846, 2013). "The transmembrane 4 superfamily member 5 protein (TM4SF5) has been implicated in hepatocellular carcinoma (HCC)." (PMID 22427965, 2012). "TM4SF5, one of the tetraspanins, was previously implicated in hepatocellular carcinoma (HCC)." (PMID 25268742, 2014). "Among its members, TM4SF1 and TM4SF5 are frequently overexpressed in various tumors, including hepatocellular carcinoma (HCC) and prostate cancer, where they promote EMT-associated signaling and are regarded as important therapeutic targets 21-23." (PMID 41356204, 2026). "The transmembrane 4 superfamily member 5 protein (TM4SF5) has gained attention as a target for hepatocellular carcinoma (HCC) therapy because it induces uncontrolled growth of human HCC cells via the loss of contact inhibition." (PMID 22427965, 2012). "Transmembrane 4 L six family member 5 (TM4SF5) is involved in hepatocellular carcinoma (HCC) development and progression." (PMID 40186033, 2025). "On the other hand, most studies have confirmed the expression and involvement of TM4SF5 in hepatocellular carcinoma (HCC), CRC, and PC." (PMID 36678607, 2023). "Xenografts using endogenously TM4SF5-expressing hepatoma PLC/PRF/5 cells resulted in significantly less tumor volumes upon treatment of TcxC peptides, compared with those upon control TCsr peptide treatment." (PMID 34335982, 2021). "TM4SF1 and TM4SF5 play roles in both cell proliferation leading to hepatocellular carcinoma and migration and invasion in cancer metastasis." (PMID 28129652, 2017). "Transmembrane 4 L six family member 5 (TM4SF5) is highly expressed in hepatocellular carcinoma tissues and enhances migration in two-dimensional environments." (PMID 29137358, 2017). "The expression of either TM4SF1 or TM4SF5 is enhanced compared with normal tissues in many different types of cancer, including hepatocellular carcinoma." (PMID 28129652, 2017). "Transmembrane 4 superfamily member 5 protein (TM4SF5) is a potential therapeutic target for hepatocellular carcinoma (HCC) and colon cancer." (PMID 27816969, 2016). "TM4SF5 is highly expressed in hepatocellular cancer tissues, and enhances their aberrant proliferation, migration, and invasion of hepatocytes." (PMID 25033048, 2014). "TM4SF5 is involved in cancers such as hepatocellular carcinoma (HCC) and colon cancer." (PMID 27816969, 2016). "Another TAL6 family protein, TM4SF5, is overexpressed in hepatocellular carcinoma and colon cancer." (PMID 26621839, 2016). "Therefore, TM4SF5 in hepatocytes may modulate homoeostatic blood glucose levels as shown in this study, although hepatic TM4SF5 also play roles in the development of pathological phenotypes for non‐alcoholic fatty liver disease and hepatocellular carcinoma." (PMID 36063136, 2022). "In addition, we have examined whether xenografts by endogenously TM4SF5-expressing hepatoma cells were also affected by the peptides." (PMID 34335982, 2021). "Because this binding can be abolished by cell-penetrating peptides containing the TM4SF5 C-terminus, targeting this direct interaction may be an effective strategy for developing therapeutics that block the development and progression of hepatocellular carcinoma." (PMID 34335982, 2021). "Hepatocellular carcinoma (HCC) recurrence or metastasis appears to be critical for poor survival of HCC patients with TM4SF5 expression." (PMID 34335982, 2021). "Transmembrane 4 superfamily member 5 protein (TM4SF5) is presumed to serve as a molecular target to prevent or treat hepatocellular carcinoma (HCC) and colon cancer in a mouse model." (PMID 25268742, 2014).
hepatocellular carcinoma (continued). "In this study, we identified a B cell epitope peptide from hepatocellular carcinoma (HCC)-specific transmembrane 4 superfamily member 5 (TM4SF5) protein that potently induced epitope-specific antibodies." (PMID 21592346, 2011). "It is reported that TM4SF4 and TM4SF5 could promote hepatocellular carcinoma (HCC) cell growth and metastasis both in vivo and in vitro." (PMID 33015133, 2020). "Transmembrane 4 L6 family member 5 (TM4SF5) is overexpressed during CCl4-mediated murine liver fibrosis and in human hepatocellular carcinomas." (PMID 25033048, 2014). "TM4SF5 expression is positively correlated with tumorigenic CD151 expression, but is negatively correlated with tumor-suppressive CD63 expression in mouse fibrotic and human hepatic carcinoma tissues, indicating cooperative roles of the tetraspanins in liver malignancies." (PMID 25033048, 2014).
liver cancer (13 papers, 2014 to 2025). An epithelial or non-epithelial malignant neoplasm that arises from the liver. "A higher expression of TM4SF5 alone or in combination with mTOR can be associated with poor recurrence-free survival in patients with liver cancer." (PMID 35955521, 2022). "Tumor tissues from liver-orthotopically xenografted mice fed a high protein diet or human liver cancer tissues showed TM4SF5-dependent macropinocytosis and NCOA3-correlated metastatic features, unlike mice fed a normal chow diet or human nontumor regions." (PMID 40186033, 2025). "We also investigated the antitumor activity of Ab27 in nude mice bearing liver cancer xenografts of SNU-398 cells expressing endogenous TM4SF5." (PMID 35211652, 2022). "In a previous study, we observed that the intratumoral injection of Ab27 decreased tumor growth in nude mice bearing TM4SF5-overexpressing SNU-449T7 (liver cancer) subcutaneous xenografts." (PMID 35211652, 2022). "TM4SF5-transgenic and diethylnitrosamine (DEN)-induced liver cancer mouse models exhibited fibrotic and cancerous livers, respectively, with enhanced TM4SF5, pY705STAT3, collagen I, and laminin γ2 levels." (PMID 34921636, 2021). "Direct binding of TM4SF5 to L-arginine with an EC50 of 10.48–37.9 μM suggests that TM4SF5 is a physiological sensor of lysosomal arginine in liver cancer cells." (PMID 31956272, 2020). "TM4SF4 is upregulated in injured liver in CCl4-treated mice, overexpressed in liver cancer tissues, and is correlated with directional migration, similar to TM4SF5." (PMID 28129652, 2017). "Transmembrane 4 L six family member 5 (TM4SF5), a transmembrane glycoprotein belonging to the transmembrane 4 L six family, is highly expressed in diverse cancers including hepatic cancer." (PMID 29137358, 2017). "In addition to TM4SF5-positive liver tissue from patients with HCC showing obvious ALB levels, patients with liver cancer (LIHC) from TCGA datasets showed a positive correlation between TM4SF5 and hepatic ALB levels." (PMID 40186033, 2025). "Future research could explore therapies that block TM4SF5 to prevent liver cancer growth and spread." (PMID 40186033, 2025). "TM4SF5, as a physiological sensor of lysosomal arginine in liver cancer cells, contributes to the SLC38A9-dependent efflux of arginine, so anti-TM4SF5 reagents could be used as a strategy for impairing arginine auxotrophs in HCC." (PMID 35955521, 2022). "The peptides may still be promising molecules for use in targeting TM4SF5 and c-Src in liver cancer." (PMID 34335982, 2021). "Evidence also suggests that TM4SF5-facilitated arginine trafficking may contribute to liver cancer recurrence." (PMID 31956272, 2020). "Thus, it is likely that TM4SF5 chronically drives different steps of liver diseases, eventually leading to hepatic cancer and metastasis." (PMID 28458469, 2017). "In addition, TM4SF5, another member of the four-transmembrane-domain family, was observed to be highly expressed in human liver cancer tissues and cells." (PMID 26709920, 2015). "We next examined the relationship between CD151, CD63, and TM4SF5 in human liver cancer tissues." (PMID 25033048, 2014). "Furthermore, TM4SF5 is highly expressed in various cancer types, including liver cancer." (PMID 35955521, 2022). "Additionally, because hepatocellular carcinoma can arise from liver fibrosis/cirrhosis, it is reasonable to hypothesize that TM4SF5 overexpression in liver cancer tissues could be involved in liver fibrosis." (PMID 28458469, 2017). "Analysis of LIHC data from TCGA further showed the functional relationship between TM4SF5 and SLAMF7 in liver cancer." (PMID 39828766, 2025). "As TM4SF5 is known to bind and activate FAK 24 and c-Src family kinases (SFKs) 25, we confirmed the binding of endogenous FAK and c-Src to exogenous TM4SF5 in hepatic cancer cells." (PMID 34335982, 2021). "TM4SF5-positive liver cancer cells show reduced expression of IL6, and TM4SF5 is induced by TGFβ1-mediated signaling." (PMID 29137358, 2017).
liver cancer (continued). "TM4SF5 interacts with IL6R, leading to STAT3 activation independent of IL6 in hepatic cancer cells." (PMID 34921636, 2021).
colon carcinoma (9 papers, 2012 to 2025). "Expression of TM4SF5 is thus likely to be associated with onset or progression of colon cancer cells and TM4SF5 can be a target to treat colon cancer." (PMID 25268742, 2014). "Another study demonstrated that combining humanized anti-TM4SF5 mAb and TM4SF5-specific peptide-based vaccine can strengthen their anticancer impact and reduce the metastatic potential of colon cancer in vivo." (PMID 38533510, 2024). "By contrast, flow cytometry and immunofluorescence analyses showed that Ab27 recognized TM4SF5 on CT26 mouse colon cancer cells." (PMID 35211652, 2022). "To improve the clinical potential of this antibody, in this study, we evaluated the therapeutic potential of Ab27 using endogenous or stably TM4SF5-expressing liver and colon cancer cells in vivo and in vitro." (PMID 35211652, 2022). "In this study, we evaluated the therapeutic potential of the Ab27 chimeric monoclonal antibody against liver and colon cancer cells expressing endogenous levels of TM4SF5 or stably overexpressing the protein in vitro and in vivo." (PMID 35211652, 2022). "In summary, we evaluated the therapeutic potential of the anti-TM4SF5 chimeric antibody Ab27 using liver and colon cancer cells expressing TM4SF5 in vitro and in vivo." (PMID 35211652, 2022). "The injection of the humanized anti-TM4SF5 antibody significantly suppressed metastatic tumor growth in the lung suggesting that the antibody suppressed re-localization and growth of colon cancer cells in lung tissue." (PMID 27816969, 2016). "We previously confirmed that treatment with the anti-TM4SF5 monoclonal antibody reduced the growth of human and mouse colon cancer cells." (PMID 27816969, 2016). "Based on these results, we conclude that the humanized anti-TM4SF5 monoclonal antibody can attenuate lung metastasis of colon tumors in a mouse model." (PMID 27816969, 2016). "We also confirmed that E-cadherin and β-catenin expression was increased by anti-TM4SF5 monoclonal antibody treatment in human colon cancer cells." (PMID 27816969, 2016). "Here, we found that the treatment of colon cancer cells with the humanized anti-TM4SF5 antibody significantly reduces their migration capability, based on the results from migration and wound healing assays." (PMID 27816969, 2016). "Taken together, these results suggest that immunization with the TM4SF5 peptide vaccine can attenuate lung metastasis of colon tumors in the mouse model." (PMID 27816969, 2016). "Then, we assessed the effect of the TM4SF5 peptide vaccine on the growth of lung tumors induced by intravenous injection of CT-26 colon cancer cells." (PMID 27816969, 2016). "Analysis of the results of xenograft experiments revealed that the anti-TM4SF5 monoclonal antibody targeting colon tumor cells can decrease tumor growth in vivo." (PMID 25268742, 2014). "The obtained results demonstrate that this anti-TM4SF5 monoclonal antibody has therapeutic effects in mouse models of colon cancer, and suggest that injection with anti-TM4SF5 antibody can be an efficacious therapeutics to treat colon cancer in humans." (PMID 25268742, 2014). "Using mouse colon cancer models, we then evaluated the in vivo anti-cancer effect of anti-TM4SF5 antibody." (PMID 25268742, 2014). "Here, we investigated expression of the TM4SF5 protein in colon cancer tissues in detail and confirmed that the TM4SF5 protein is overexpressed in human colon cancer tissues." (PMID 25268742, 2014). "Almost all of the colon cancer tissues expressed TM4SF5 based on immunohistochemistry using anti-TM4SF5 monoclonal antibody." (PMID 25268742, 2014). "Based on the tumor volume and weight, anti-TM4SF5 monoclonal antibody attenuated the progression of colon tumors compared with PBS or normal mouse IgG." (PMID 25268742, 2014). "As the anti-TM4SF5 monoclonal antibody can inhibit the growth of colon cancer cell lines in vitro, we next investigated the in vivo effect of the antibody on tumors." (PMID 25268742, 2014).
colon carcinoma (continued). "To evaluate the efficacy of the anti-TM4SF5 antibody against colon cancer in mice, we determined the effect of the anti-hTM4SF5 antibody on the growth of colon cancer cells in vivo using human cell line HT-29 and a xenograft mouse model." (PMID 25268742, 2014). "To validate TM4SF5 as an efficacious target for anti-colon cancer therapy, we first examined the expression of TM4SF5 mRNA in human colon cancer cell lines." (PMID 25268742, 2014). "We confirmed that injection of anti-TM4SF5 antibody reduced the growth of tumors derived from pre-implanted colon cancer cells in mice." (PMID 25268742, 2014). "To confirm the anti-tumor activity of the anti-TM4SF5 monoclonal antibody against colon cancer in vivo, we administered the anti-TM4SF5 antibody into mice bearing tumors pre-established by injection with human or mouse colon cancer cells." (PMID 25268742, 2014). "To investigate the effect of anti-TM4SF5 antibody on colon tumors, we used mouse CT-26 cells and a mouse tumor allograft model." (PMID 25268742, 2014). "We therefore validated anti-TM4SF5 monoclonal antibody as an efficacious therapeutic against colon cancer in vivo using mouse xenograft and allograft models." (PMID 25268742, 2014). "In this study, we investigated expression of TM4SF5 in colon cancer tissues and the therapeutic effect of the TM4SF5-specific monoclonal antibody against colon cancer in a mouse model." (PMID 25268742, 2014). "The treatment of human colon cancer cells with anti-TM4SF5 antibody reduced growth of TM4SF5 expressing cells and enhanced expression of E-cadherin and β-catenin." (PMID 25268742, 2014). "We also confirmed that the anti-TM4SF5 antibody inhibited growth of human colon cancer cell lines expressing TM4SF5." (PMID 25268742, 2014). "Based on the immunohistochemistry data of colon cancer tissue microarrays, TM4SF5 expression was detected in almost all of the colon cancer tissue samples we examined, at various expression levels." (PMID 25268742, 2014). "Treatment with the anti-TM4SF5 antibody significantly suppressed the progression of colon tumors derived from CT-26 cells." (PMID 25268742, 2014). "Expression of TM4SF5 was also detected in a mouse colon cancer cell line CT-26, as previously reported, and therefore CT-26 cells were used for a mouse allograft model." (PMID 25268742, 2014). "Together these experiments suggest that the anti-TM4SF5 monoclonal antibody can inhibit growth of colon tumors in an allograft mouse model." (PMID 25268742, 2014). "The expression of TM4SF5 in colon tumor tissue was confirmed by immunostaining with the anti-TM4SF5 antibody." (PMID 25268742, 2014). "This is the first report directly showing expression of TM4SF5 protein in a large number of colon cancer tissues." (PMID 25268742, 2014). "Approximately 35.6% of colon cancer tissue samples expressed TM4SF5 in ≥75% of tumor cells and ~40% of colon cancer tissues were positive for TM4SF5 expression in 74-50% of tumor cells." (PMID 25268742, 2014). "In order to investigate expression of the TM4SF5 protein in colon cancer tissues, we performed immunohistochemical staining with the anti-TM4SF5 monoclonal antibody." (PMID 25268742, 2014). "The mRNA expression of TM4SF5 in human cancer is prevalently observed in pancreatic cancer, soft tissue csarcoma, gastric cancer, carcinoma of the papilla vateri, and colon cancer." (PMID 22427965, 2012). "The Ab27-based ADC exhibited dramatic antitumor activity in vitro and in a colon cancer xenograft model (S.K., unpublished data), suggesting that Ab27-based ADCs could serve as potent therapeutics for the treatment of TM4SF5+ cancers." (PMID 35211652, 2022). "TM4SF5 is a novel therapeutic target for liver and colon cancers." (PMID 35211652, 2022). "Therefore, we investigated the antitumor efficacy of Ab27 in nude mice bearing colon cancer xenografts of HT-29 cells expressing endogenous TM4SF5." (PMID 35211652, 2022).